BRAF (B-Raf proto-oncogene, serine/threonine kinase)
Diseases named in the same sentence as BRAF in open-access papers (continued):
Sharing a sentence is not in itself a finding about the gene and the disease.
cancer (continued). "HIPPO pathway inactivation serves as a lineage-dependent rheostat controlling the magnitude of the adaptive relief of feedback responses to MAPK inhibitors in BRAF-V600E cancers." (PMID 36476495, 2022). "Regarding the capability of KRAS and BRAF mutant tumors to create an immunosuppressive microenvironment by interfering with the cancer-immunity cycle, various studies have shown that MEKi can restore an immune stimulatory and anti-tumorigenic microenvironment." (PMID 35965494, 2022). "While DU-4475 is a mono-driver cancer cell line, solely dependent on BRAF for survival and proliferation, MDA-MB-231 relies on both the MAP kinase pathway and Src signaling." (PMID 36011019, 2022). "ZNF767P, a pseudogene on chromosome 7, has been reported to be differentially expressed in human cancers and to be translated when fused with oncogenic genes (e.g., BRAF)." (PMID 35712126, 2022). "MD Anderson Cancer Center in Texas published their Arab patients’ data describing that KRAS/NRAS/BRAF prevalence were 44.4%, 4%, and 4%, respectively, compared to 48.4%, 4%, and 4%, respectively, in the matched Western population." (PMID 35619874, 2022). "KRAS wild-type cancers had lower GALNT6 mRNA expression levels than KRAS mutated cancers, whereas BRAF mutated tumors had lower GALNT6 mRNA expression levels than BRAF wild-type tumors." (PMID 35692787, 2022). "We recently demonstrated that IL-8 production by cancer cells in vitro is tightly regulated at multiple levels and is strongly dependent on the genetic landscape (i.e., BRAF and PTEN status)." (PMID 36289899, 2022). "Although they only showed modest clinical efficacy as single agents, they had a significant anti-cancer impact when combined with BRAF inhibitors." (PMID 35234863, 2022). "Given that BRAF activity is elevated in SPOP-mutated cancers, elucidation of the SPOP-BRAF regulatory axis in further studies will be helpful in designing therapeutic strategies for SPOP-mutated cancers." (PMID 36585710, 2022). "Approximately 30% of all human cancers have mutations in the MAPK pathway and approximately 7% are mutations in the RAF kinase gene, BRAF." (PMID 35565240, 2022). "The latest NSCLC guideline 2021 V2 edition issued by the national comprehensive cancer network (NCCN) indicated that genes associated with targeted therapy of NSCLC include EGFR, KRAS, ALK, ROS1, MET, BRAF, RET, and NTRK." (PMID 35227278, 2022). "BVD-523 (Ulixertinib) is a MAPK3/1 kinase inhibitor that inhibited xenograft growth in multiple cancer types and synergized with BRAF inhibitors in BRAF mutant cell lines." (PMID 35887124, 2022). "This strategy should be more effective (multi-pathway inhibition) in a greater proportion of patients (BRAF or NRAS mutated) than existing targeted therapies, and should minimize the development of cancer cell resistance." (PMID 35158973, 2022). "For stage I‐III cancer patients, either a RAS or BRAF mutation was detected in 24/56 (42.9%) of requested LPs; for stage I–II patients, LP was positive in 9/22 (40.9%) of cases, and in 1/5 (20%) of cases for stage I." (PMID 34873826, 2022).
cancer (continued). "The lower detection levels for BRAF and EGFR mutations on the Idylla system with the cBioPortal for Cancer Genomics dataset can be attributed to the fact that most of the identified variants are rare and/or non-pathogenic." (PMID 35627184, 2022). "Oncogenic BRAF can stimulate changes that allow for immune escape of cancer cells via activation of MAPK/ERK signaling." (PMID 36430176, 2022). "In-frame insertion of three residues on ɑC-β4 loop of BRAF in cancers assembles a large hydrophobic network that involves in R-spine, which impairs BRAF dimerization and MEK inhibitor association." (PMID 35966590, 2022). "The relationship between YAP and the RAF/MEK/ERK cascade was discovered by genetic screens, which showed that the inhibitory combination of RAF or MEK with YAP has increased efficacy not only in BRAF-mutant cancers but also in KRAS-mutant cancers." (PMID 36483040, 2022). "Recent studies showed that up to 15 and 8% of human cancers harbor an activating mutation in the proto-oncogene RAS and BRAF." (PMID 35585049, 2022). "The dynamic transcriptional nature of the kinome also differs for inhibitors targeting different kinase signaling pathways (e.g., BRAF-MEK-ERK versus PI3K-AKT) that are commonly activated in cancers." (PMID 34958800, 2022). "Initially described in 2002, BRAF mutations lead to constitutive activation of the kinase BRAF and, consequently, of the RAF-MEK-ERK signaling cascade, promoting cell proliferation and survival, while inhibiting apoptosis, ultimately driving cancer growth." (PMID 35272691, 2022). "We conducted a systematic review to detect all BRAF alterations of defined functional class across different cancer types." (PMID 35884534, 2022). "Among these, six cancers had additional genetic alterations: BRAF fusions (n = 2), and one each with RET fusion plus BRCA2 loss of function mutation, IDH1 mutation, RAF1 fusion, and EML4-NTRK3 fusion." (PMID 36124727, 2022). "Newer BRAF inhibitors in development which avoid the paradoxical activation of wild type BRAF mediated by current inhibitors in use are also expected to advance therapeutics of these difficult to treat, resistant cancers." (PMID 36079062, 2022). "Gain-of-function mutations affecting the Ras/BRAF/MEK/ERK1/2 and PI3KCA/AKT/mTOR pathways have been identified in many types of cancer and VAs." (PMID 35574555, 2022). "As soon as cancer cells have a large amount of active Ras, the drug-loaded BRAF(V600E) will dimerize with CRAF and activate its catalytic activity, which has been referred to as the paradoxical effect of RAF inhibitors." (PMID 36499382, 2022). "Compelling evidence indicates that the heparanase (HPSE) gene has multiple functions in cancer, however, its role in BRAF V600E-mutant CRC remains elusive." (PMID 36130926, 2022). "Both KRAS and BRAF are downstream EGFR oncogenes, for which their mutations can activate EGF receptor signalling in cancer cells and are linked with poor prognosis in the CRC." (PMID 35782059, 2022). "The presented analyses explore the properties of oncogenic BRAF mutations and will help to further delineate the complex role of BRAF in cancer." (PMID 36275468, 2022). "BRAF signalling has been studied extensively in relation to cancer because of its oncogenic potential, but the role of BRAF in the heart has remained relatively unexplored." (PMID 35147166, 2022). "Aberrant activation of ERK signaling is a hallmark of many cancers, and is most commonly due to mutations of RAS and BRAF genes." (PMID 36500607, 2022). "Most targeted cancer therapies are targeting specific somatic mutations, such as EGFR, BRAF, VEGF and BRCA mutations in various cancers." (PMID 36457740, 2022). "THCA harbored the highest number of fusion transcripts, of which SND1_BRAF was the most common one, while other cancer types such as LIHC, LUSC, STAD, KIRP, LGG, and BLCA had equally few fusion transcripts." (PMID 35910024, 2022).
cancer (continued). "A final interesting finding of the current investigation with potential future therapeutic implications is the identification of a NUAK family kinase (NUAK) inhibitor as one of the top hits in the pan-cancer BRAF mutant cell line screening." (PMID 36295658, 2022). "Using this method, researchers found that cancer‐related EGFR‐L858R (EGFR, epidermal growth factor receptor) and BRAF‐V600E mutations with allelic fractions as low as 0.1% can be detected in cell‐free DNA fragments." (PMID 35845351, 2022). "And EGFR, VEGFR and BRAF targets in MAPK signaling pathway has been extensively studied for promising cancer treatment." (PMID 35439731, 2022). "We analyzed fusion transcripts of BRAF across various cancer types by using the TCGA Fusion Gene Database." (PMID 35910024, 2022). "BRAF inhibition (BRAFi) therapy is a form of MAPK inhibitor (MAPKi) therapy used to treat cancer patients with mutant BRAF." (PMID 35725577, 2022). "BRAF/PIK3CA double mutant cancers had higher rates of chromosomal stability than BRAF mutant cancers with wild type PIK3CA." (PMID 36079062, 2022). "For stage I‐III cancer patients, either a RAS or BRAF mutation was detected in 24/56 (42.9%) of requested LPs, while LP was positive in 9/22 (40.9%) cases for stage I–II patients, and for 1/5 (20%) stage I cases." (PMID 34873826, 2022). "It selectively infects cancer cells and replicates due to active RAS signaling pathway, K-Ras, BRAF, and EGFR mutations in cancer cells." (PMID 35686109, 2022). "In this study, we profiled BRAF expression, fusion transcript, alteration, and the prognostic and clinical implications across 32 TCGA cancer types." (PMID 35910024, 2022). "Mutations in PTPRD, CREBBP, BRAF, NOTCH3, TERT, and SETD2, which are involved in various aspects of immune regulation, were reported as potential biomarkers in cancer patients after immunotherapy with improved survival." (PMID 36092890, 2022). "The CpG Island Methylator Phenotype (CIMP) is more prevalent in BRAF mutant cancers than in BRAF wild type cancers." (PMID 36079062, 2022). "In a past report, superior efficacy of encorafenib compared to dabrafenib was found using an in vitro cytotoxicity assay measured across a panel of BRAF-mutant cancer cell lines." (PMID 35486732, 2022). "BRAF inhibitors such as vemurafenib, dabrafenib, and encorafenib are currently used to treat patients with BRAF-mutant cancers." (PMID 36585710, 2022). "Taken together, the author employed publically available data from the AACR Project GENIE to explore the complex role of BRAF in cancer." (PMID 36275468, 2022). "The combination of PLX4032 and HDAC inhibitors have been displayed complete elimination of cancer cells, and to reduce the progress of resistance to BRAF inhibitors." (PMID 35936102, 2022). "As a result of the V600E mutation, BRAF and its pathway are activated and are strongly associated with CIMP-positive cancers." (PMID 36595848, 2022). "To address this issue, we imaged mouse models of BRAF-mutant cancers, fluorescent KI tracers, and unlabeled drug to calibrate in silico spatial PK/PD models." (PMID 35486732, 2022). "This is a critical issue common to other kinase inhibitors targeting signaling molecules expressed in both cancer and immune cells (e.g., BRAF, AKT, mTOR inhibitors)." (PMID 36341345, 2022). "Previous studies on BRAF expression in cancer have used inconsistent research methods and have been limited to small sample sizes and/or to single or limited cancer types." (PMID 35910024, 2022). "BRAF mutant cancers have been divided in two subsets, based on unsupervised genomic clustering, that do not correlate with their MSI status or PIK3CA mutation status." (PMID 36079062, 2022).
cancer (continued). "As expected, prior targeted therapy, which was overwhelmingly EGFR-targeted, increased the proportion of cancers with BRAF V600E (12.6% vs. 6.5%, p = 0.019) and ERBB2 amplification (5.9% vs. 2.3%, p = 0.043)." (PMID 35621667, 2022). "The results revealed that the expression profiles of BRAF and downstream genes were generally negatively correlated with methylation in various cancers." (PMID 35910024, 2022). "Since developed, several ERK inhibitors (ERKi) have been shown to be active against different cancers harboring RAS, BRAF, or MEK mutations, as well as cancers with developed BRAF/MEK inhibitor resistance 7-11." (PMID 36276640, 2022). "Small molecule inhibitors have been successfully developed to target BRAF and MEK in cancers with oncogenic mutations in the RAS–RAF–MEK–ERK pathway." (PMID 35899070, 2022). "Currently, three BRAF inhibitors are approved in Europe and US for the treatment of patients with BRAF-mutant cancers, namely vemurafenib, dabrafenib and encorafenib." (PMID 35158933, 2022). "Although OV and LUAD harbored similar alteration frequencies, the functional profiles of BRAF in these two cancers were quite different, with different amplification and mutation patterns." (PMID 35910024, 2022). "The combined BRAF alteration (CNV and mutation) frequency in all cancers was about 8.3% (905 of 10,967 samples)." (PMID 35910024, 2022). "A BRAF point mutation in V600E is commonly reported in KRAS wild-type PDAC, and targeting BRAF_V600E is already being applied to various carcinomas, including PDAC." (PMID 36505826, 2022). "In this study, four identified compounds were selected ZINC70454679, ZINC253500968, ZINC106887736, and ZINC107434492 through the virtual screening as a potential lead candidates for BRAF protein overexpression related carcinoma." (PMID 36267655, 2022). "The only way forward is to include multiple cancer types and stratify or limit studies to single cancer types and document the molecular subtypes (e.g., BRAF status within melanoma BM), accepting this will lead to smaller studies." (PMID 34765539, 2021). "The GDSC data set had a total of 47 unique drugs with ten targets, including EGFR, IGF1R, HDAC1, PARP2, AURKA, and BRAF, as well as their sensitivities across 224 cancer cell lines." (PMID 33795761, 2021). "The established canine TCC cell lines responded with greater sensitivity to sorafenib than to vemurafenib, which is known as a specific BRAF inhibitor in human cancer." (PMID 34502061, 2021). "For high frequency mutated genes of specific subtype, gene BRAF in type I encodes a protein belonging to the RAF family of serine/threonine protein kinases, which have been identified in various cancers." (PMID 34068143, 2021). "FGF/FGFR-dependent STAT3 activity has been correlated with resistance to doxorubicin, 5-fluorouracil, cisplatin, paclitaxel, and MEK/BRAF inhibitors in several cancers." (PMID 34830951, 2021). "It was worth pointing out that such studies claimed synergistic effect between BRAF inhibitors and EZH2 inhibitors in a subset of cancers that had EZH2 amplification or gain-of-function mutations which led to re-distribution of H3K27me3." (PMID 33713851, 2021). "Inhibiting the BRAF(V600E) or STAT3 pathway or modulating cancer cell autophagy was also reported to sensitize cancer cells to NK cell cytotoxicity." (PMID 34072732, 2021). "Autophagy is a cellular recycling process, which has been shown to allow cancer cells to escape from BRAF inhibition." (PMID 34298710, 2021).
cancer (continued). "Our lead PROTAC outperforms vemurafenib in inhibiting cancer cell growth and shows in vivo efficacy in a Class 2 BRAF xenograft model." (PMID 33568647, 2021). "Another report showed in preclinical models that combining a BRAF dimer inhibitor with an MEK inhibitor induced a dramatic therapeutic effect and overcame acquired resistance among cancers with KRAS, NRAS, NF1, BRAF non-V600E, and BRAF V600E mutations." (PMID 34063682, 2021). "Altogether, ~80% of drug resistant cases in BRAF(V600E)-harboring cancers arise from pathway reactivation of ERK signaling." (PMID 35582307, 2021). "These functional observations are also in line with our finding that BRAF/EGFR-mutant lung tumors are recurrently found across different cancer centers, indicating a basis for the co-existence of BRAF/EGFR mutations without selection pressure." (PMID 34921211, 2021). "Survival tree for cluster 3 featured TMB, BRAF and KRAS mutation status and cancer stage as predictors." (PMID 34600575, 2021). "We estimate KRAS is mutated in only 11% of all cancers, which is less than PIK3CA (13%) and marginally higher than BRAF (8%)." (PMID 34645806, 2021). "BRAF phosphorylates ERK via MEK in cancer cells, and phospho-ERK phosphorylates its downstream targets, which include NRF2." (PMID 34069882, 2021). "Preclinical models looking for synergy have shown positive effects combining CDK4/6i with inhibitors targeting molecules such as EGFR, MEK, mTOR or BRAF V600E in various cancers, as well as the ability to overcome resistance." (PMID 34138895, 2021). "Anti-EGFR antibodies have limited, if any activity against BRAF V600E mutant cancers, unless combined with a BRAF inhibiting agent." (PMID 34407800, 2021). "We discuss current treatment with BRAF inhibitors (BRAFi) with secondary cancer side effects and resistance development." (PMID 34066966, 2021). "Most known cancer genes have been found through primary cytogenetic analyses, although sequencing of cancer genomes has revealed new cancer genes including BRAF, EGFR, ERBB2, PIK3CA, PPP2R1A, and JAK2." (PMID 34298667, 2021). "We therefore sought to better molecularly characterize the mechanisms of resistance to single and combined MEKi and ERKi in oncogenic KRAS-, HRAS- or BRAF-driven cancer cells by focusing analyses on potential rewiring of intracellular signaling cascades." (PMID 33924486, 2021). "Such adaptive resistance mechanisms are suggested in many cancer cells as well as in induced pluripotent cancer cells (iPCCs) which are highly resistant to the RAS/BRAF/ERK kinase pathway inhibitors vemurafenib and trametinib." (PMID 33613844, 2021). "BRAF which plays a role in the oncogenesis of several malignant tumors, is also involved in a small proportion of IDH-wt GB." (PMID 34804975, 2021). "Shown by large genomic database analysis using GENIE and cancer alteration databases in cBioPortal, 5767 cases harbored BRAF alterations, 3761 of which belong to class 1, 529 class 2, 651 class 3, and 282 BRAF fusions, with the remaining unclassifiable." (PMID 33507258, 2021). "For cluster 2, cancer stage, grade, radiotherapy, TMB, BRAF mutation status were important predictors." (PMID 34600575, 2021). "The most common missense mutation of BRAF (mainly V600E) is known to constitutively activate the MAPK pathway and contributes to the incidence of various cancers." (PMID 34578339, 2021). "We observed that BRCA1/2 gene alterations were mutually exclusive with amplification of all the oncogenes examined in the breast (CCND1, CCNE1 and CDC6) and ovarian (CCND1, CCNE1 and BRAF) cancer cohorts." (PMID 34389725, 2021). "Matrix remodelling by fibroblasts exposed to BRAF inhibitors can also impair the response of cancer cells to the treatment." (PMID 34298736, 2021). "Consistent with our analysis in fibroblasts, SCARNA15 expression was remarkably higher in cancer cells with MYC alterations compared to those harbouring KRAS and BRAF mutations." (PMID 34316713, 2021).